PARP1 (poly(ADP-ribose) polymerase 1)
Diseases named in the same sentence as PARP1 in open-access papers (continued):
Sharing a sentence is not in itself a finding about the gene and the disease.
Stroke (43 papers, 2009 to 2025). Sudden impairment of blood flow to a part of the brain due to occlusion or rupture of an artery to the brain. "To screen, we conducted a protein mass spectrometry to explore potential molecular mechanisms underlying the effects of delayed PARP-1 inhibition on the post-stroke inflammation." (PMID 32317937, 2020). "Studies have shown that ischemic stroke leads to the production of reactive oxygen species that result in overstimulation of PARP-1, an important cause of cell death in in-vivo models of stroke." (PMID 33321687, 2020). "In adult stroke models, male and female Parp-1-deficient mice both display a reduction in Parp-1 and AIF production, suggesting the activation of the caspase-independent apoptotic pathway by both sexes." (PMID 22474588, 2012). "In addition, Sirt1 increases the activity of DNA repair pathways such as the poly [ADP-ribose] polymerase 1 (PARP1) pathway associated with stroke." (PMID 36076942, 2022). "These markedly affected biological processes and pathways might account for the similarities and differences underlying the effects of PARP-1 inhibition in post-stroke inflammation." (PMID 32317937, 2020). "Collectively, these studies suggest that the loss of SirT1 function in post‐stroke muscle is likely due to overactivation of PARP‐1 that could have utilized most of the available intracellular NAD+ needed for SirT1 activity." (PMID 32676579, 2020). "In the current study, stroke represses SirT1 activity and that loss of SirT1 function may increase the activity of PARP‐1 in post‐stroke muscle." (PMID 32676579, 2020). "However, only male Parp-1-deficient animals exhibited a reduction in stroke-induced brain damage following MCAO." (PMID 22474588, 2012). "PARP1 KO mice display schizophrenia-like behaviors, have impaired memory formation, and have defects in neuronal proliferation and survival, while mutations in genes that affect PARylation have been associated with intellectual disability, psychosis, neurodegeneration, and stroke in humans." (PMID 34708032, 2021). "Overactivation of PARP-1 is an important mechanism leading to tissue damage in various pathological conditions associated with oxidative stress, including myocardial reperfusion injury, stroke, and shock, while PARP-1 inhibitors showed pronounced protection against these diseases." (PMID 27027354, 2016). "PARP-1 knockout in mice resulted in smaller infarcts and better neurological outcomes after stroke induced by MCAO." (PMID 40558537, 2025). "In 7-day-old mice, a stroke lesion induced by MCAO activated PARP-1 in a sexually dimorphic manner, and PARP-1 gene deletion only protected males." (PMID 40558537, 2025). "CREBBP, NFE2L2 and PARP1 are known for their roles in the pathogenesis of stroke and post-stroke neurovascular remodeling and functional recovery." (PMID 34992531, 2021). "In the current study, we found a novel mechanism for PARP‐1 in promoting muscle atrophy, especially in post‐stroke muscle." (PMID 32676579, 2020). "In this study, we attempted to investigate the effects of delayed PARP-1 inhibition on post-stroke neuro-inflammation and behavioral performance in male and female mice." (PMID 32317937, 2020). "In diseases, PARP-1 has been shown to be involved in stroke, ischemia diabetes and other inflammatory diseases." (PMID 32344695, 2020). "This study was aimed to investigate the effects of delayed PARP-1 inhibition on post-stroke inflammation and possible sexual dimorphism, and explore the possible relevant mediators." (PMID 32317937, 2020). "PARP-1 inhibitor also displays exciting therapeutic potential in experimental and clinical stroke studies." (PMID 32317937, 2020). "Overall, previous studies mainly focused on the effects of immediate PARP-1 inhibitor administration on post- stroke inflammation." (PMID 32317937, 2020). "It is worthy to note that the regulatory effects of delayed PARP-1 inhibition on post-stroke inflammation are comparable in males and females." (PMID 32317937, 2020).
Stroke (continued). "Further investigations are needed to identify the detailed mechanisms of the sex-specific effects of PARP-1 inhibition in stroke." (PMID 32317937, 2020). "In support, neuronal death following stroke and traumatic brain injury is found to stem in part from the overactivation of PARP-1 due to massive DNA damage." (PMID 33424554, 2020). "Stroke increased the expression of the ZNF216 gene in PTA muscle by activating PARP‐1, which binds on the ZNF216 promoter." (PMID 32676579, 2020). "In this study, we compared the innate gender-based proclivity in response to delayed PARP-1 inhibition in the experimental stroke." (PMID 32317937, 2020). "The increase in PARP1, MMP9 and HMGB1 associated with stroke in SHRs points to the unique relationship between hypertension and the enhancement of post-stroke cell death." (PMID 33214598, 2020). "In conclusion, we for the first time investigated the effects of delayed PARP-1 inhibition on post-stroke inflammation in males versus females." (PMID 32317937, 2020). "We demonstrate that stroke activates PARP‐1 that binds on the ZNF216 promoter to increase the ZNF216 gene expression." (PMID 32676579, 2020). "PARP1 inhibitors are also being used in more than 100 clinical trials for cancer therapy and for clinical implications such as stroke and cardiac infarction." (PMID 30271949, 2018). "Parp1 activity is known to exacerbate the severity of many neurodegenerative diseases, including stroke and Alzheimer’s disease." (PMID 28886188, 2017). "For example, RNF146 has been shown to be neuroprotective against DNA damage, N-methyl-D-aspartate (NMDA)-induced excitotoxicity, and stroke, all of which induce neuronal damage via overactivation of PARP1 enzymatic activity and PAR polymer synthesis." (PMID 29290984, 2017). "RNF146 has been shown to be neuroprotective against PAR polymerase-1 (PARP1)-induced cell death during stroke." (PMID 29290984, 2017). "In a number of severe and acute diseases such as stroke, neurotrauma, circulatory shock, and acute myocardial infarction, activation of PARP-1 is detectable in human tissue samples supporting the clinical application of PARP-1 inhibition." (PMID 28698869, 2017). "In fact, Parp-1 inhibition increased stroke damage in intact females and estrogen-replaced ovariectomized females, again suggesting a mediating role of estrogen." (PMID 22474588, 2012). "In a neonatal-stroke mouse model, disruption of the PARP-1 gene selectively protected male mice against brain injury." (PMID 20196871, 2010). "More studies are still required to address this issue and understanding the roles played by PARP-1, calpains and VEGFs in post-ischemic cerebral angiogenesis is an area of drug development, particularly for stroke therapy." (PMID 21176168, 2010). "Because PARP1 dependent cell death plays a pivotal role in the progress of stroke, pharmacological inhibition of PARP1 can eliminate inflammation, protect neurons, regulate the translocation of apoptosis-inducing factor, and improve recovery of neurological functions in ischemic stroke." (PMID 36438061, 2022). "Furthermore, poly(ADP-ribose) polymerase-1 (PARP-1) inhibition reduced infarcts in males but exacerbated injury in females in a transient stroke model, again demonstrating the importance of examining both sexes." (PMID 34359998, 2021). "This study was commenced by investigating whether delayed PARP-1 inhibition could mitigate post-stroke inflammation and neurological deficits, and whether there was a sex bias in the effects of PARP-1 inhibition." (PMID 32317937, 2020). "Efforts need to be made to delineate the actions of PARP-1 inhibition in stroke, and here we propose that Prx1 might be a critical mediator." (PMID 32317937, 2020). "This study has shown that delayed treatment of PARP-1 inhibitor at 48 h after ischemic stroke could prominently suppress microglial activation, and mitigate both post-stroke neuro-inflammation and neurological deficits." (PMID 32317937, 2020).
Stroke (continued). "However, more significant reduction of iNOS and MMP9 induced by PARP-1 inhibition and better neurological functions were found in male MCAO mice, indicating gender differences of PARP-1 inhibitor treatment for stroke." (PMID 32317937, 2020). "Finally, we confirmed that SirT1 inhibits ZNF216 gene expression by blocking PARP‐1 activity and that inhibition likely plays a role in reversing post‐stroke muscle atrophy." (PMID 32676579, 2020). "In male and female C57BL/6 mice subjected to transit middle cerebral artery occlusion (MCAO), we found that delayed treatment of PARP-1 inhibitor at 48 h following reperfusion could comparably alleviate neuro-inflammation at 72 h after stroke." (PMID 32317937, 2020). "We found that stroke caused a significant increase in the expression of PARP1 in the brain homogenate of SHRs, an effect that was not present in normotensive animals." (PMID 33214598, 2020). "It has been reported that PARP1 inhibitors also inhibit MMPs, indicating that the beneficial effects of PARP1 inhibitors after stroke may be in part due to the inhibition of MMPs53." (PMID 33214598, 2020). "Indeed, PARP1 activation has been reported in stroke, and excess stimulation-induced excitotoxicity in cortical and striatal neurons." (PMID 29290984, 2017). "Interestingly, injection of recombinant Prx1 into the ischemic core could block the anti-inflammatory effects of PARP-1 inhibitor in the experimental stroke." (PMID 32317937, 2020). "Thus, it is reasonable to determine the regulation and role of PARP‐1 in post‐stroke muscle." (PMID 32676579, 2020). "Thus, our results indicated that PARP-1 inhibitor might attenuate neuro-inflammation by targeting the microglial activation after stroke." (PMID 32317937, 2020). "However, it is controversial that whether gender dimorphism exists in the neuroprotective effects of PARP-1 inhibitor in stroke." (PMID 32317937, 2020). "Moreover, there is preclinical evidence showing that PARP-1 inhibitors would be beneficial in acute diseases, such as stroke, traumatic brain injury, circulatory shock, and acute myocardial infarction, as well as in chronic diseases such as chronic heart failure and asthma (reviewed by Curtin)." (PMID 26339143, 2015). "In addition to the role of PARP-1 in DNA repair, multiple studies have also demonstrated its involvement in several inflammatory diseases, such as septic shock, asthma, atherosclerosis, and stroke, as well as in cancer." (PMID 26339143, 2015). "PARP-1 inhibition also reduced apoptosis-inducing factor nuclear translocation and cell death in an adult rat model of MCAO stroke." (PMID 40558537, 2025). "For instance, cell death because of injury, such as stroke, is mediated by caspases in females, whereas the process is commonly dependent on Poly (ADP-ribose) polymerase 1 (PARP-1) and the nitric oxide (NO) pathway in males." (PMID 37238932, 2023). "The large protection seen in PARP2−/− mice was unexpected because PARP2 is less abundant than PARP1, suggesting a complex interaction between PARP1 and PARP2 in the context of stroke." (PMID 34025565, 2021). "According to the results obtained in another research group using a rat stroke model, nuclear GAPDH that translocates to the nucleus under oxidative/nitrosative stress mediates brain damage by binding with nuclear poly(ADP-ribose) polymerase-1 (PARP-1)." (PMID 34827652, 2021). "Eight studies have used PARP1-null mice (PARP1−/−) and PARP2-null mice (PARP2−/−) to investigate the role of PARPs in stroke with models of MCAO." (PMID 34025565, 2021). "PARP-1 inhibition undoubtedly rescues cells from necrotic cell death, but the role(s) played by MMP inhibition in stroke clearly deserve further study." (PMID 21176168, 2010). "This suggests SARM1 mediates post-stroke neuronal death primarily through regulating NAD+ metabolism rather than PARP1 activation, providing new insights into targeting SARM1 to protect neurons." (PMID 41272776, 2025).
Stroke (continued). "The exogenous recombinant Prx1 could block the inhibitory effects of PJ34 on post-stroke inflammation in the male MCAO mice,as the reduction of Iba-1, iNOS, and TNF-α mRNA levels induced by PARP-1 inhibition were reversed by Prx1." (PMID 32317937, 2020). "We further demonstrate that stroke activates PARP‐1 protein that increases muscle levels of ZNF216, but not MuRF1 and Atrogin1 gene expressions at the transcriptional level." (PMID 32676579, 2020). "Importantly, conduction of clinical trials with drugs directed at PARP1-NAD+ pathway deserves strong priority, particularly to preserve quality of life and to attenuate devastating complications such as heart failure or stroke." (PMID 30898999, 2019). "Recently, the pharmacokinetics of a PARP-1 inhibitor (TES448, TES Pharma, Corciano, Italy) has been significantly improved and published data revealed a robust neuroprotective effect in an adult rat stroke model." (PMID 28698869, 2017). "Currently no PARP-1 inhibitors are in use for stroke treatment." (PMID 36681688, 2023). "Furthermore, we discuss novel druggable targets for AF and highlight future directions for clinical trials with drugs directed at DNA damage-PARP1-NAD+ axis with the ultimate aim to preserve quality of life and to attenuate severe complications such as heart failure or stroke in patients with AF." (PMID 32411727, 2020). "Poly(ADP-ribose) polymerase 1 (PARP-1) is a family of nuclear enzymes with diverse functions in chromatin structure, transcription, and genomic integrity, and it plays a role in the inflammatory pathogenesis of many central nervous system disorders including stroke." (PMID 33321687, 2020). "Moreover, PARP-1 is an important regulator of neuronal cell death and cellular responses to DNA damage and it has been reported that PARP-1 mediated cell death is dependent on androgen-receptor signaling after stroke." (PMID 29311911, 2017). "Indeed, Parp1 deletion has been shown to protect male, but not female, animals against stroke and autoimmune-nephritis." (PMID 28978150, 2017). "Moreover, PARP-1 inhibitor was administrated at 48 h following ischemia/referfusion, in order to comfirm that whether PARP-1 inhibitor could potentially provide an extended time window for stroke treatment." (PMID 32317937, 2020). "In this study, PARP-1 inhibitor PJ34 was given to male and female MCAO mice at 48 h after MCAO, and our results demonstrated that delayed delivery of PJ34 could significantly block post-stroke microglial activation, alleviate neuro-inflammation in male and female MCAO mice." (PMID 32317937, 2020).
cervical carcinoma (42 papers, 2012 to 2025). A carcinoma arising from either the exocervical squamous epithelium or the endocervical glandular epithelium. "XIAP, an apoptosis inhibitor directly restraining the caspase activity, exhibits an apoptosis inhibitory function in cervical cancer cells because its deficiency leads to upregulated cleaved caspase-3 and PARP1 protein levels." (PMID 39408613, 2024). "A significant relationship between Val762Ala polymorphism in PARP-1 and the induced risk of cervical cancer in Caucasian women was also reported." (PMID 30020984, 2018). "Poly (ADP-Ribose) Polymerase 1 (PARP-1) has been implicated in several processes that promote cellular proliferation of lung and cervical cancer cells." (PMID 25003966, 2014). "In this study, we found for the first time that the PARP-1 Ala762Ala(GCG/GCG) genotype significantly contributes to cervical carcinoma susceptibility, which further extend the important role of PARP-1 in carcinogenesis." (PMID 22624032, 2012). "MA-PCR was used to genotype the PARP-1 Val762Ala polymorphism in 539 women with cervical carcinoma, 480 women with CIN and 800 controls." (PMID 22624032, 2012). "The increased risk of cervical carcinoma in subjects with the PARP-1 Ala762Ala(GCG/GCG) genotype is likely attributable to the reduction of PARP-1 activity." (PMID 22624032, 2012). "In HPV positive population, the PARP-1 Ala762Ala genotype was also associated with increased risk of cervical carcinoma (OR: 5.56, 95% CI: 2.08–14.3)." (PMID 22624032, 2012). "And PARP1 Val762Ala polymorphism may be an independent prognostic factor for cervical cancer, which might play a role in the prediction of clinical results." (PMID 29152079, 2017). "However, women carrying the PARP-1 Ala762Ala genotype were significantly susceptible to cervical carcinoma (OR: 2.70, 95% CI: 1.47–3.70), and the similar results were also found in squamous cell carcinoma (OR: 2.56, 95% CI: 1.47–3.70)." (PMID 22624032, 2012). "Our results indicate that the PARP-1 Ala762Ala genotype increases the risk of cervical carcinoma." (PMID 22624032, 2012). "The aim of this study was to determine whether the PARP-1 Val762Ala polymorphism is associated with the risk of cervical carcinoma." (PMID 22624032, 2012). "In comparison to these studies, our findings suggest that CpG-ODNs may alleviate renal injury caused by cervical cancer radiotherapy (RKI) by inhibiting the activation of the PARP1/XRCC1 signaling axis, thus suppressing DNA damage and oxidative stress responses in renal tubular epithelial cells." (PMID 37773127, 2023). "In addition, HPV positive subjects with the PARP-1 Ala762Ala(GCG/GCG) genotype had stronger association with risk of cervical carcinoma, implying that interaction of HPV infection with the genetic variation of host jointly contributes to the cervical carcinogenesis." (PMID 22624032, 2012). "PARP-1 expression correlates with β-catenin levels, and its inhibition has been shown to enhance cisplatin-induced cytotoxicity in cervical cancer cells via the modulation of the β-catenin signaling pathway." (PMID 39940959, 2025). "The Western blotting results showed that MCPIP1 but not C306R overexpression reduced the protein levels of XIAP but increased cleaved caspase-3 and cleaved PARP1 in cervical cancer cells." (PMID 39408613, 2024). "Our Western blotting assay demonstrated that XIAP knockdown in HeLa and SiHa cells led to increased expression of cleaved caspase-3 and cleaved PARP1, verifying its apoptosis-resistant function in cervical cancer cells." (PMID 39408613, 2024). "We verified the success of the anoikis model of cervical cancer cells through changes in the precursors and shears of PARP1 and Caspase-3 since PARP1 is the marker of apoptosis and the primary target of Caspase-3." (PMID 37403143, 2023). "Bioinformatics analysis revealed that the downstream targets regulated by CpG-ODNs in cervical cancer RKI were primarily PARP1 and XRCC1." (PMID 37773127, 2023).